BMP7 (bone morphogenetic protein 7)
Diseases named in the same sentence as BMP7 in open-access papers (continued):
Sharing a sentence is not in itself a finding about the gene and the disease.
fibrosis (18 papers, 2008 to 2023). the formation of excess fibrous connective tissue in an organ or tissue in a reparative or reactive process. "We utilized in vivo bleomycin-induced fibrosis models in the skin and lung to determine the potential therapeutic effect of BMP-7." (PMID 19112509, 2008). "Therefore, it is possible that BMP-7 reduced cardiac fibrosis and adverse myocardial remodeling through transforming growth factor (TGF-β1)." (PMID 34685620, 2021). "It was hypothesized that repeated BMP-7 injections into the knee joint might induce adverse effects such as synovial fibrosis, ectopic cartilage and bone formation, or osteophyte formation." (PMID 18826579, 2008). "Bone morphogenetic protein-7 (BMP-7), a member of the TGF-β superfamily, can reduce glomerular and tubulointerstitial fibrosis and is considered to be a protective factor in DN." (PMID 37762992, 2023). "Bone morphogenetic protein-7 (BMP7) exerted potent anti-fibrotic actions in vitro, and in pre-clinical fibrosis models." (PMID 34439762, 2021). "Emerging candidate biomarkers for CKD progression include surrogates of tubulointersitital injury (NGAL, IL-18, KIM-1, EGF), tubulointerstitial fibrosis (MMP-9, PIIINP, TGF-β1, BMP-7), and inflammation (MCP-1, TNFR 1/2, suPAR)." (PMID 33108507, 2021). "Fibrosis, histopathological features, serum creatinine (sCr), BUN, and renal mRNA expression of αSMA, Col-1α, TGF-β1, CTGF, BMP7, IL-1, TNFα, VEGF and PAX2 were analyzed." (PMID 33275619, 2020). "Furthermore, we observed that the expression level of TGF-β1 was reduced whereas the expression level of BMP-7 was enhanced in liver tissues of DWYG-treated rats, therefore the expression ratio of TGF-β1/BMP-7 was dramatically decreased compared to CCl4-induced fibrosis model rats." (PMID 25345787, 2014).
lung cancer (18 papers, 2010 to 2025). A malignant neoplasm involving the lung. "Encouragingly, we also found this TUBB3+CD68 TAM subset in a 10× scRNA-seq dataset of human non–small cell lung cancer (NSCLC) biopsy with strong expression of neuronal genes including BMP7, SHANK, CHL1, and PAX6." (PMID 36206343, 2022). "Several reports have demonstrated that BMP7 promoted cell invasiveness and motility of lung cancer cells." (PMID 34036102, 2021). "Most BMPs/BMP receptors were downregulated in lung cancer tissues, except BMP7, ACVR1C, and ACVR2B which were upregulated in one dataset." (PMID 34036102, 2021). "Previous studies have shown that the expression of BMP7 was related to lymph node metastasis in patients with lung cancer." (PMID 34036102, 2021). "BMP-7 also attenuates the effect of TGF-β or silica on EMT in cholangiocarcinoma or lung cancer cells, respectively." (PMID 32141512, 2020). "A recent publication indicated that BMP7 plays a key role in the regulation of lung cancer progression, linking its expression level to lymph node involvement." (PMID 24299561, 2013). "The aim of this study is to investigate the effect of BMP7 on proliferation of lung carcinoma cells and explore the roles of different types of I receptors in BMP7 signal transmission by blocking endogenous BMPRIs." (PMID 20673479, 2010). "Furthermore, they showed that re-expression of BMP7 substantially reversed the tumor suppressive effects of miR-137 on lung cancer cell proliferation, migration, and invasion." (PMID 28407692, 2017). "The roles of BMP4 and BMP7 in lung cancer may be controversial." (PMID 32750747, 2020). "However, the regulation of BMP7 by miRNAs was only recently reported in lung cancer." (PMID 28407692, 2017). "All male mice receiving BMP-7-treated A-549 cells also developed masses that histologically consisted of solid neoplasms consistent with the histological origin of the tumor cell line, lung carcinoma and were comprised of a nodule or shell of ectopic bone containing active bone marrow." (PMID 23675191, 2010). "At present, approximately 20 BMPs have been identified; however, most studies involving BMPs in lung cancer have focused on BMP2, BMP4, and BMP7." (PMID 34745928, 2021). "It has been demonstrated that BMP7 has metastasis role in regulating lung cancer cell motility and invasion without influencing cell growth, proliferation, or apoptosis, Overexpression of BMP7 also promotes immunotherapy resistance." (PMID 40098956, 2025). "In addition, they identified BMP7 as a target of miR-137 in lung cancer cells, and used a luciferase reporter assay to show that miR-137 directly targeted 3'-UTR of BMP7." (PMID 28407692, 2017). "Finally, we identified BMP5 as having significantly differential expression and superior prognostic value, rather than BMP2, BMP4, and BMP7, which have been extensively explored in lung cancer." (PMID 34745928, 2021). "BMP7 signaling via BMPR1A and BMPR1B could inhibit the proliferation of lung cancer cells." (PMID 34036102, 2021). "Some researches demonstrate that BMP4 and BMP7 enhance invasion and metastasis of lung cancer while others do not, which may need to be further confirmed." (PMID 32750747, 2020). "It has been demonstrated that bone morphogenetic protein 7 (BMP7) may both inhibit and enhance cell proliferation of many kinds of cancers, but the impact of BMP7 on lung cancer cells and the exact mechanisms are not clear." (PMID 20673479, 2010).
colorectal cancer (17 papers, 2009 to 2025). A primary or metastatic malignant neoplasm that affects the colon or rectum. "The peak at 20 q13.31 encodes BMP7, a member of the TGFâ superfamily of proteins whose overexpression in colorectal cancer significantly correlates with markers of pathological aggressiveness such as liver metastasis and is an independent prognostic factor of overall survival." (PMID 22860045, 2012). "It has been reported previously that elevated BMP7 expression was significantly associated with increased depth of tumour invasion, metastasis to liver, liver recurrence and advanced Dukes' classification (staging system used in colorectal cancer) in colorectal cancer." (PMID 37688374, 2023). "Resveratrol possesses anticancer activity through upregulating the bone morphogenetic protein 7 (BMP7) in order to inactivate the PI3K/Akt signaling pathway through partly suppressing the phosphorylation of PTEN in colorectal cancer." (PMID 34744708, 2021). "For instance, BMP7 was reported to function as a potent tumor suppressor in gastric carcinoma, renal cell carcinoma, lung and colorectal cancer, and osteosarcoma." (PMID 34680590, 2021). "BMP7 is a regulator involved in the maintenance of the stem cell niche and related to poor prognosis in colorectal cancer patients." (PMID 28347289, 2017). "In addition, high BMP-7 expression could be a useful predictive marker of poor prognosis in patients with lung cancer, esophageal squamous cell carcinoma, colorectal cancer, and clear cell renal carcinoma." (PMID 27661009, 2016). "Yao and co-workers demonstrated that ANGPTL4 up-regulates bone morphogenetic protein 7 (BMP7), therefore, inhibiting apoptosis of colorectal cancer cells and promoting metastasis." (PMID 30049845, 2018). "The present study has focused exclusively on the effects of four gene knockdown on drug sensitivity in colorectal cancer cells, without delving into the molecular mechanisms through which three of these key genes – BAMBI, MAPK8IP2, and BMP7 – regulate oxaliplatin sensitivity." (PMID 41395597, 2025).
osteoporosis (16 papers, 2017 to 2024). A condition of reduced bone mass, with decreased cortical thickness and a decrease in the number and size of the trabeculae of cancellous bone (but normal chemical composition), resulting in increased fracture incidence. "It has been reported that BMP-7 deletion leads to death and its deficiency induces different diseases such as osteoporosis." (PMID 31979268, 2020). "High dose BMP2 or BMP7 need to be administrated systemically to treat bone loss or osteoporosis, that posses a risk of systemic adverse effect." (PMID 30159139, 2018). "Local prophylactic augmentation of the proximal femur with a BMP-7 loaded thermoresponsive hydrogel during index surgery of an osteoporotic fracture could be suitable to reduce the risk of further osteoporosis-associated secondary fractures." (PMID 31488155, 2019). "BMP-7, a commonly used drug to treat osteoporosis in patients, has been tested in animal models of atherosclerosis and found to have anti-inflammatory and anti-fibrotic properties in the heart, muscle, and kidney." (PMID 36829889, 2023). "In this study, we identified BMP‐7 a growth factor belonging to the transforming growth factor‐β superfamily, commonly given to osteoporosis patients as a potential therapeutic agent." (PMID 36945866, 2023). "Collectively, Runx1 maintains adult bone homeostasis from bone loss though up-regulating Bmp7/Alk3/Smad1/5/8/Runx2/ATF4 and WNT/β-Catenin signaling pathways, and targeting Runx1 potentially leads to novel therapeutics for osteoporosis." (PMID 33476325, 2021). "Therefore, our study aimed to investigate the effects of recombinant human proteins PDGF-BB and BMP-7 on the progression of osteoporosis in oophorectomized animals." (PMID 38540737, 2024). "Therefore, BMP-7 was used for the treatment of osteoporosis, a widespread condition affecting several millions of people worldwide." (PMID 31979268, 2020). "However, the BMP-7 induced osteogenic response resulted in greater heterogeneity in the nano-structural crystal dimensions and this effect was more pronounced with osteoporosis." (PMID 29371668, 2018). "In addition, considering the demonstrated effect of BMP7 on bone morphology and structure, it can be suggested that BMP7 plays a role in the managing of osteoporosis in chronic colitis, and thus, its therapeutic potential in the treatment of IBD should be further evaluated." (PMID 37626658, 2023). "Systemic treatment with recombinant proteins for five weeks, involving two weekly applications of 30 μg/kg of BMP-7 and 20 μg/kg of PDGF-BB, was effective in partially reversing osteoporosis." (PMID 38540737, 2024). "We evaluated the effects of recombinant human BMP-7 (rhBMP7) and PDGF-BB (rhPDGF-BB) in an oophorectomy-induced osteoporosis rat model." (PMID 38540737, 2024). "Except for anti-osteoporosis drugs, it has been reported that the systemic administration of FGF-1 (fibroblast growth factor-1) and BMP-7 (bone morphogenetic protein-7) promote the healing of osteoporotic fractures." (PMID 37622974, 2023). "Furthermore, the histological data also indicate that the most effective treatments for osteoporosis were the administration of zoledronic acid and PDGF-BB and BMP-7 1×/week." (PMID 38540737, 2024). "BMP-7, a member of the BMP family, has demonstrated remarkable potential in bone fracture repair and can induce osteoblast differentiation even more effectively than PTH hormone, a widely used therapeutic alternative for osteoporosis treatment." (PMID 38540737, 2024). "Runx1 maintained adult bone homeostasis and bone differentiation though upregulating Bmp7/Alk3/Smad1/5/8/Runx2/ATF4 and WNT/β-Catenin signaling pathways, suggesting that targeting Runx1 might be a novel therapeutics for osteoporosis." (PMID 37156809, 2023). "OVX-induced osteoporosis is characterized by high bone turnover and it can be speculated that the large callus volumes are a product of the upregulated anabolism of OVX coupled with the potent anabolic effect of BMP-7." (PMID 27822590, 2017).
osteoporosis (continued). "Considering the determined effect of BMP7 treatment on the RANKL/RANK/OPG system, trabecular number, and separation, it can be suggested that BMP7 affects long bone morphology, density, and structure and, therefore, could have an impact on the managing osteoporosis in chronic colitis." (PMID 37626658, 2023).
pulmonary fibrosis (16 papers, 2008 to 2024). Chronic progressive interstitial lung disorder characterized by the replacement of the lung tissue by connective tissue, leading to progressive dyspnea, respiratory failure, or right heart failure. "BMP7 is capable of reducing expression of vimentin in the silica-induced lung fibrosis model and inhibiting EMT through suppressing TGF-β/Smad2/3 pathways." (PMID 39142248, 2024). "Although BMP members have been revealed to play an anti-fibrotic function in several different organs, BMP4 and BMP7 are the most intensively studied in pulmonary fibrosis." (PMID 39142248, 2024). "BMP7 opposes TGFβ1-mediated collagen induction in mouse pulmonary myofibroblasts and inhibits silica-induced lung fibrosis in rats." (PMID 25849157, 2015). "BMP-7 may also inhibit pulmonary fibrosis by activating the BMP-7/Smad pathway and concurrently inhibiting the TGF-β/Smad pathway." (PMID 38970048, 2024). "Further, BMP7 has been shown to alleviate silica-induced pulmonary fibrosis in rats." (PMID 39142248, 2024). "Similarly, in a model of pulmonary fibrosis induced with asbestos, treatment with BMP-7 decreased the hydroxyproline levels, counteracting its antagonist Gremlin, whose levels are elevated in fibrotic lungs." (PMID 24781156, 2014). "On the other hand, BMP7 was ineffective to treat skin and lung fibrosis suggesting that the antifibrotic effects of BMP7 may be organ dependent." (PMID 23799103, 2013). "Additionally, A2AR may play a role in reducing fibrosis involved in cardiac pathological remodelling and pulmonary fibrosis through the Rap1 or BMP7/Smad1/5 signalling pathway." (PMID 38057890, 2023). "Therefore, the combination of anti-TLR signaling and upregulation of Bmp7 by MHP1-AcN might be ideal for the prevention of bleomycin-induced pulmonary fibrosis." (PMID 35864207, 2022). "Therefore, we sought to investigate whether in vivo administration of BMP-7 would reduce lung fibrosis." (PMID 24781156, 2014). "Other studies suggest that BMP-7 is less effective at inhibiting TGF-β1 for both in vivo and in vitro BLM-induced skin and lung fibrosis models, suggesting that perhaps renal models show the best reduction in fibrosis by BMP-7." (PMID 34445632, 2021). "BMP7 was proven to decrease silica-induced pulmonary fibrosis through modulation of the balance between suppression of TGFβ/SMAD and activation of the BMP7/SMAD signaling pathway." (PMID 31547567, 2019). "In models of lung disease, similar opposing actions of BMP7 on TGF-β/Smad signaling were indicated by reduced p-Smad 2/3 levels and attenuation of silica-induced pulmonary fibrosis in animals treated with recombinant BMP7." (PMID 28620300, 2017). "Thus, BMP-7 may have the potential for nickel-induced lung fibrosis." (PMID 29127306, 2017). "Taken together we have shown that BMP-7 has no anti-fibrotic effect in lung fibrosis either at the in vivo or in vitro level." (PMID 19112509, 2008). "The hypothesis of a Smad-dependent pathway rather than a non-canonical pathway-mediated effect of BMP7 is also supported by other studies, even in pulmonary fibrosis where BMP7 would act through a Smad1/5/8-Id2 and Id3 signalling pathway." (PMID 29295498, 2017). "However, despite continual treatment for 14 days, the progression of lung fibrosis was not modified, suggesting that in lung cells, the inhibitory effects of BMP-7 are absent." (PMID 19112509, 2008). "Therefore BMP-7, although active, was not therapeutic in our models of lung fibrosis at the efficacious doses used in this study." (PMID 19112509, 2008). "However, Knight’s team discovered that BMP7 could not protect against bleomycin-induced lung fibrosis." (PMID 39142248, 2024).
acute kidney injury (15 papers, 2008 to 2025). Sudden and sustained deterioration of the kidney function characterized by decreased glomerular filtration rate, increased serum creatinine or oliguria. "We believe that the development of growth factor mimetics, and in particular the BMP-7 mimetics, offers great promise for the treatment of acute kidney injury and other serious debilitating diseases." (PMID 35873578, 2022). "The level of BMP-7 is significantly reduced while increased levels of BMP-7 expression can inhibit EMT in various animal models of acute kidney injury or chronic renal fibrosis." (PMID 35721136, 2022). "IRI, which in the present investigation was used as a model for acute kidney injury, resulted in a significant reduction of the potential kidney protective factors, klotho and BMP7." (PMID 34061900, 2021). "In inflammatory bowel disease and acute renal failure, BMP7 treatment reduces the severity of the pathogenesis and favors healing." (PMID 18816401, 2008). "This is supported by the fact that BMP-7 null mice die perinatally from renal failure." (PMID 19112509, 2008). "In addition, the expression of BMP-7 was decreased in renal failure." (PMID 36909186, 2023). "To test this hypothesis, we embarked on a project wherein we designed and developed peptide mimetics of Bone Morphogenetic Protein-7 (BMP-7) for the treatment of Acute Kidney Injury (AKI)." (PMID 35873578, 2022). "Others have also found that BMP7 treatment led to significant reductions in proinflammatory cytokines, including TNF, in macrophages in vivo and that BMP7 represses TNF and IL1B in models of chronic and acute renal failure and in chondrocytes from patients with osteoarthritis." (PMID 32973129, 2020).